LEP (leptin)
Diseases named in the same sentence as LEP in open-access papers (continued):
Sharing a sentence is not in itself a finding about the gene and the disease.
polycystic ovary syndrome (62 papers, 2009 to 2026). A disorder that manifests as multiple cysts on the ovaries. "Reproductive age women with polycystic ovary syndrome also have hyperandrogenic sex hormone profiles that were associated with higher levels of leptin and lower levels of adiponectin." (PMID 36712262, 2022). "For many years, leptin/LepR-deficient mice, such as db/db mice, have been used as animal model to study polycystic ovary syndrome (PCOS), which is widely acknowledged as the most frequent female endocrine disorder, with a variety of etiological factors and clinic manifestations." (PMID 26529315, 2015). "Controversies regarding the association of leptin with polycystic ovarian syndrome (PCOS) exist." (PMID 22851226, 2013). "Elevated serum leptin levels were reported in overweight/obese women with PCOS, and are linked to hyperandrogenemia and IR, key features of the syndrome." (PMID 39858399, 2024). "The main aim of the presented research project is to assess the concentration of vitamin D, calcium, and selected hormones as well as the concentration of adipokines (leptin) in girls diagnosed with polycystic ovary syndrome." (PMID 36246904, 2022). "High leptin levels can inhibit aromatase activity, which is a key enzyme in the conversion of androgens to estradiol, further aggravating hyperandrogenemia, which affects follicle growth and development, resulting in ovulation dysfunction." (PMID 35355566, 2022). "In turn, in adolescents with polycystic ovary syndrome, leptin concentration depends on BMI, adipose tissue content, waist circumference and HOMA-IR value." (PMID 36246904, 2022). "Hormone dysregulation (e.g. leptin, ghrelin, resistin, adiponectin), insulin resistance, low levels of sex hormone-binding proteins, high androgen levels, chronic inflammation, and polycystic ovary syndrome (PCOS), are associated with obesity and can lead to ovulatory dysfunction." (PMID 40789178, 2025). "Leptin may have important implications in polycystic ovary syndrome (PCOS)-related metabolic disorders." (PMID 35355566, 2022). "Previous studies have found that lower levels of phosphorylated STAT3 in GCs may be related to ovarian leptin resistance and decreased fertilization in polycystic ovarian syndrome women." (PMID 29899261, 2018). "Additionally, it has been demonstrated that high circulating leptin levels in obese women with polycystic ovarian syndrome promote OB-Rb expression in luteinized granulosa cells." (PMID 26053184, 2015). "Plasma leptin levels were reported to be negatively associated with EDV measured by forearm plethysmography in the elderly subjects, and with FMD of the brachial artery in patients with nonalcoholic fatty disease and polycystic ovarian syndrome." (PMID 24410779, 2014). "LEP is a regulatory molecule involved in the polycystic ovary syndrome (PCOS) cell model and acts as an upstream regulator of JAK1/STAT3-related inflammation and apoptosis in insulin-treated ovarian granulosa cells (OGCs)." (PMID 38005265, 2023). "Both leptin and its membrane and soluble receptors play an important role in polycystic ovary syndrome (PCOS) and female reproduction." (PMID 36289764, 2022). "Increased leptin concentration observed in women diagnosed de novo with polycystic ovary syndrome, as well as positive correlations between leptin and HOMA-IR, IRI/glucose, and BMI, may indicate a potential role of leptin in the reduction of tissue sensitivity to insulin." (PMID 34604014, 2021). "Furthermore, a study involving triptorelin treatment provided evidence that hyperandrogenemia may increase the level of the adipokine leptin (in addition to leptin influencing androgens)." (PMID 33488512, 2020). "Two suggested mechanisms that may explain further our results involve leptin and the presence of overt or undiagnosed polycystic ovary syndrome (PCOS)." (PMID 38498127, 2024).
polycystic ovary syndrome (continued). "Polycystic ovary syndrome (PCOS) patients have high concentrations of follicular phase luteinizing hormone, insulin resistance, and high leptin concentrations, which may increase miscarriage and decrease implantation rates." (PMID 33613685, 2021). "When comparing median protein concentrations adult PCOS women with or without hyperandrogenemia, the most profound differences were observed for leptin (P < 0.001), DPP-IV (P = 0.005), and adiponectin (P < 0.001)." (PMID 27806063, 2016). "On the contrary, a recent study demonstrated that there were no changes in fasting serum leptin despite improvement in body composition after ten weeks of high-intensity interval training in young women with polycystic ovary syndrome." (PMID 27774458, 2016). "Moreover, 2-Hz EA treatment in rats with polycystic ovary syndrome has been shown to restore the expression of leptin in visceral adipose, but does not affect serum leptin concentrations." (PMID 33868169, 2021). "Furthermore, studies have found a correlation between serum leptin levels and expression levels of Testosterone, estradiol (E2), follicle-stimulating hormone (FSH), and Aromatase (P450)arom in women with hyperandrogenism and Polycystic ovary syndrome (PCOS)." (PMID 35027962, 2021). "The positive correlation of leptin with testosterone and the negative correlation of adiponectin with the three studied androgens was found only in females and mimics the hormonal and metabolic interplay described in polycystic ovary syndrome." (PMID 33163464, 2020). "Finally, with regard to direct effects of altered leptin signaling components in oocyte maturation, SOCS3 mRNA was shown to be decreased in human CC collected from patients with polycystic ovary syndrome (PCOS)." (PMID 33924072, 2021).
Cachexia (60 papers, 2006 to 2026). Severe weight loss, wasting of muscle, loss of appetite, and general debility related to a chronic disease. "Systemic approaches include lowering leptin levels (via weight loss or pharmacologic modulation) to reduce SOCS3-driven resistance, or supplementing leptin in deficiency states such as cachexia." (PMID 41516046, 2025). "Leptin is an adipokine that has been implicated in the development of cachexia, and several studies have investigated the relationship between leptin and cachexia in head and neck cancer patients." (PMID 38534979, 2024). "The results showed an association between cell infiltration and decreased leptin levels, suggesting an inflammatory role in the modulation of this hormone during cachexia." (PMID 39596015, 2024). "Collectively, in our model, BC-derived miR-204 induced cancer-associated cachexia by reprogramming hypoxia and leptin signalling pathway to trigger lipolysis by targeting Vhl in white adipose tissue." (PMID 37620316, 2023). "Elevated circulating levels of cytokines, such as leptin, are an important cause of uremia-associated cachexia via signaling through the central melanocortin system." (PMID 35326490, 2022). "The investigators concluded that in men with HF, leptin (possibly reflecting cachexia) explained the inverse association between mortality and excess weight." (PMID 36428528, 2022). "Our metabolic and transcriptomic response signature sets of infection in the leptin mutant and WT controls can assist in the further study of the mechanisms underlying the role of leptin in glucose homeostasis, wasting syndrome and defense against infection." (PMID 35933481, 2022). "In this respect, metabolic changes due to leptin deficiency are also relevant for understanding T2DM that is accompanied by wasting syndrome." (PMID 34233759, 2021). "Leptin is important for the pathogenesis of disease-associated cachexia such as cancer cachexia, chronic heart failure-induced cachexia, pulmonary cachexia, aging-associated cachexia and CKD-associated cachexia." (PMID 34440723, 2021). "Previously, we reported that modulation of the central melanocortin signaling by leptin is an important cause of CKD-associated cachexia." (PMID 34440723, 2021). "Clinical studies have not demonstrated conclusive results about the potential role of leptin in cachexia and lean body mass loss, and low leptin levels were associated with mortality in dialysis patients but not in all studies." (PMID 28333114, 2017). "Plasma glycerol and leptin associate with adipose tissue atrophy and mass, respectively; however, no study has evaluated their potential as a prognostic biomarker of cachexia-associated fat loss." (PMID 26508820, 2015). "The aim of this study was to investigate the role of leptin, ghrelin and obestatin as diagnostic and predictive markers of cachexia in oncologic patients." (PMID 25400234, 2014). "Cancer, COPD, and aging-associated cachexia are all associated with low leptin levels, in spite of low appetite and elevated energy expenditure suggesting a state of resistance to the effects of hypoleptinemia." (PMID 22518191, 2012). "Finally, the restoration of food intake via leptin deficiency prevented lethal cachexia in autophagy-deficient mice." (PMID 40060612, 2025). "It has been reported that the activation of STAT3 signaling supports lipase ATGL and its co-activator CGI-58 dependent adipocyte lipolysis and increases serum leptin levels that may influence cachexia-associated anorexia." (PMID 38245529, 2024). "Elevated leptin signaling is an important cause of chronic kidney disease-associated cachexia." (PMID 34440723, 2021). "Tonic histamine signaling might account for the apparent increase of sensitivity to anorexigenic factors, above all leptin, associated with cachexia." (PMID 31921666, 2019).
Cachexia (continued). "Based on previous research and because of the evidence of the important role played in the homeostasis of body weight regulation, we hypothesized that leptin, ghrelin and obestatin could be useful as diagnostic markers of cachexia in oncologic patients." (PMID 25400234, 2014). "Active tuberculosis is associated with cachexia, weight loss and low serum concentration of leptin." (PMID 23565890, 2013). "Our results showing a weight-loss dependent association with cachexia may support the association of leptin with cachexia." (PMID 20920199, 2010). "We hypothesize that leptin may be an important cause of INC-associated cachexia." (PMID 34440723, 2021). "Therefore, the similarities between the deficiency of leptin and tuberculosis could be related to the occurrence of wasting syndrome in both ob/ob mice and lepb mutant zebrafish larvae." (PMID 34233759, 2021). "We found 71 proteins that correlated with cachexia severity via weight loss grade, weight loss, skeletal muscle index and radiodensity (r ≥ |0.50|, p ≤ 0.05), including some known cachexia mediators/markers (LEP, MSTN, ALB) as well as novel proteins (e.g., LYVE1, C7, F2)." (PMID 33334063, 2020). "Exercise typically lowers leptin levels, and limited available evidence shows that physical activity helps reduce leptin-driven inflammation in cachexia." (PMID 40869331, 2025). "This causes the secretion of additional inflammatory factors by the AT itself, including leptin, resistin, and monocyte chemoattractant protein-1 (MCP-1), which further exacerbate systemic inflammation and metabolic dysfunction associated with cachexia." (PMID 41373779, 2025). "Another study investigated the effects of Walker 256 tumor-induced cachexia in Wistar rats, focusing on the infiltration of mononuclear cells into adipose tissue and the reduction in leptin concentration." (PMID 39596015, 2024). "In another study, frail elderly patients with manifestations of cachexia had significantly lower serum levels of leptin." (PMID 39682572, 2024). "In the states of cachexia, the leptin levels are reduced and correlate inversely with the levels of pro-inflammatory cytokines." (PMID 39337308, 2024). "Collectively, our study reveals circulating miR-204-5p induces hypoxia-mediated leptin signalling pathway to promote lipolysis and WAT browning, shedding light on both preventive screenings and early intervention for cancer-associated cachexia." (PMID 37620316, 2023). "The application of Ghrelin resulted in an increase in bodyweight in LIF-induced mice cachexia and a corresponding increase in serum leptin levels." (PMID 35740622, 2022). "CKD-associated cachexia and PEW in rats were ameliorated by a leptin antagonist, or by blockade of the leptin receptor." (PMID 35369060, 2022). "Nevertheless, it is possible that after infection of the leptin mutants as compared to the WTs, more energy is drained from long term storage supplies or depletion of muscle mass, as observed in severe wasting syndrome." (PMID 35933481, 2022). "Leptin and these inflammatory cytokines modulate hypothalamic feedback mechanisms and contribute to CKD-associated cachexia." (PMID 34440723, 2021). "The authors analyzed the expression variations of adipokines (leptin, adiponectin, and visfatin) with lipolysis-related proteins in the white adipose tissue of cachectic cancer patients and in rat models of cachexia." (PMID 32660156, 2020). "Leptin has been shown to be increased in rodents and humans exhibiting cachexia in many disease states, such as CHF." (PMID 33329046, 2020). "At the end-stage of cachexia (TC) the response was different: the leptin tissue concentration was maintained and adiponectin showed an even more pronounced decrease (P < 0.001 vs. control and IC)." (PMID 28830524, 2017). "In the middle-stage of cachexia (IC) there was a reduction in leptin gene expression and an increase in adiponectin and visfatin mRNA levels." (PMID 28830524, 2017).
Cachexia (continued). "The large inter- and intra-individual variation in levels in the present study suggests that, although leptin is indeed involved in the pathophysiology of cachexia, it cannot serve as a useful marker at one time." (PMID 25411961, 2014). "There is a scarcity of therapeutic data on patients with CHF-cachexia, so little is known about leptin responses to treatment at this time." (PMID 22518191, 2012). "Elderly patients with cachexia tend to have elevated inflammatory markers and low leptin levels, both correlating with worsened prognosis." (PMID 22518191, 2012). "The presence of adipogenic defects in adipose tissue in cachexia is further supported by the dramatic reduction in mRNA levels of leptin, a mature adipocyte marker." (PMID 17047651, 2006). "The hypothesis suggesting that cachexia and muscle wasting in COPD caused by altered energy balance may arise from dysfunctions in the leptin feedback mechanism has been explored extensively in the literature." (PMID 40283443, 2025). "Notably, leptin levels fall much more than expected based solely on fat mass reduction, which suggests an altered adipose tissue signalling in cachexia." (PMID 41373779, 2025). "The rise in leptin levels seen in patients who had a complete or partial response to treatment suggests a possible improvement in their nutritional status and a decrease in cachexia." (PMID 38534979, 2024). "The study’s results indicate that leptin may play a role in the development of cachexia in patients with HNSCC." (PMID 38534979, 2024). "Furthermore, leptin signaling increases lipolysis in white adipose tissue, promoting cachexia, a multiorgan wasting syndrome characterized by systemic inflammation accompanied by the loss of adipose tissue and skeletal muscle." (PMID 39199587, 2024). "This similarity could be explained by the occurrence of wasting syndrome in both the leptin mutants and during TB." (PMID 35933481, 2022). "The decreased circulating leptin is an important “natural” systemic response to combat LIF-induced cachexia and therefore may also be important for the mechanisms of potential cachexia therapies." (PMID 35740622, 2022). "In contrast, leptin appears to be the most interesting adipokine in the context of cachexia." (PMID 36158184, 2022). "The authors observed the lowest concentration of leptin in sera from cachectic patients, demonstrating that both leptin and BMI could be considered predictors of cachexia with accuracy exceeding 90%." (PMID 32660156, 2020). "However, additional studies on the role of leptin in cachexia and use of leptin as a biomarker are warranted." (PMID 28177923, 2017). "We have demonstrated that reduction of leptin level in cancer patients may be a consequence of catabolic changes during cachexia process." (PMID 25049439, 2014). "In addition, MCP-1, the circulating level of which was altered by SJDBT, has been known to regulate leptin level in the adipose and to mediate cachexia." (PMID 24963216, 2014). "Leptin may also contribute to CHF-cachexia and obesity-related cardiomyopathy by various cardiovascular mechanisms, including increasing sympathetic activity and producing vasodilation by an endothelium-dependent mechanism peripherally." (PMID 22518191, 2012). "Given the key role that inflammation appears to play in the pathogenesis of leptin-mediated cachexia, therapeutic intervention with anti-inflammatory drugs may prove to be beneficial in restoring sensitivity to the effect of hypoleptinemia in ACS." (PMID 22518191, 2012). "This suggests that the mechanism for cachexia in the elderly may involve disrupted hypothalamic feedback of leptin from the effects of proinflammatory cytokines like other chronic inflammatory states." (PMID 22518191, 2012). "Although leptin levels are directly associated with weight loss after fasting, associations between leptin levels and cancer related cachexia are not yet fully elucidated." (PMID 20920199, 2010).